TIGD1 (tigger transposable element derived 1)
Diseases named in the same sentence as TIGD1 in open-access papers (continued):
Sharing a sentence is not in itself a finding about the gene and the disease.
cancer (6 papers, 2021 to 2025). A tumor composed of atypical neoplastic, often pleomorphic cells that invade other tissues. "ROC analyses were conducted to assess the diagnostic significance of TIGD1 expression across pan-cancer through calculating the AUC values." (PMID 40565566, 2025). "While the exact mechanisms remain to be clarified, these associations point to TIGD1 as a potential biomarker for predicting drug response and a candidate for targeting drug resistance in cancer therapy." (PMID 40565566, 2025). "This study aimed to perform a comprehensive pan-cancer analysis of TIGD1 to evaluate its expression patterns, diagnostic utility, prognostic value, and association with immunotherapy response and drug resistance." (PMID 40565566, 2025). "In conclusion, this study represents the first comprehensive investigation into the intricate association between TIGD1 and pan-cancer." (PMID 40565566, 2025). "TIGD1 expression showed significant associations with five immune subtypes across various cancers, as assessed by TISIDB." (PMID 40565566, 2025). "The KEGG enrichment items indicated a primary association of TIGD1 expression with lysosome in 24, spliceosome in 21, and RNA transport in 20 out of 35 TCGA cancers." (PMID 40565566, 2025). "This offers insights into the multifaceted roles of DEGs associated with TIGD1 expression in both developmental and cancer contexts." (PMID 39734333, 2024). "Further analysis using the CIBERSORT algorithm revealed that TIGD1 was correlated with immune infiltration in 37 out of 39 cancer types, with notable positive associations with T follicular helper (TFH) cells and negative associations with regulatory T cells (Tregs)." (PMID 40565566, 2025). "Elevated TIGD1 expression was associated with poor prognosis in several cancers." (PMID 40565566, 2025). "Consistent with our findings, TIGD1 is an overexpressed protein across various cancer types, including LUSC, but its function, associated proteins, and cellular mechanisms remain largely unknown." (PMID 39734333, 2024). "Transposable elements, such as TIGD1, serve as the main regulators of gene expression via gene editing, through silencing, enhancing, or alternative splicing in human cancers." (PMID 40565566, 2025). "By integrating multi-omics datasets, we seek to establish TIGD1 as a candidate biomarker in cancer biology and explore its potential as a therapeutic target." (PMID 40565566, 2025). "Despite emerging evidence implicating TIGD1 in oncogenesis, its role in cancer remains largely elusive." (PMID 40565566, 2025). "This study provides a comprehensive analysis of TIGD1 across multiple cancer types, evaluating its expression patterns, prognostic significance, immune interactions, and potential implications in drug resistance." (PMID 40565566, 2025). "These divergent roles suggest that TIGD1 functions in a cancer-type-specific manner, necessitating further mechanistic studies." (PMID 40565566, 2025). "Furthermore, patients with higher TIGD1 expression exhibited increased overall survival (OS) risk scores compared to those with lower expression levels, suggesting that TIGD1 may act as an oncogene in cancer progression." (PMID 38651061, 2024). "Further research is necessary to uncover additional mechanisms and validate TIGD1’s role in cancer progression and treatment." (PMID 38651061, 2024). "Cellular studies confirmed TIGD1’s involvement in cancer cell proliferation, invasion, and migration." (PMID 38651061, 2024). "Previous studies have demonstrated the potential pivotal function of TIGD1 in cancer cell proliferation, invasion, and migration using bioinformatics techniques." (PMID 38651061, 2024). "Recently, TIGD1 was predicted as a cell-cycle-related biomarker upregulated in various cancer types and indicated a worse prognosis in these cases." (PMID 34858497, 2021).
cancer (continued). "Given TIGD1’s transposable origin, its overexpression in various cancers, and preliminary evidence linking it to immune infiltration, we aimed to explore its immunological relevance across cancer types." (PMID 40565566, 2025). "Notably, this study also establishes a strong link between TIGD1 expression and drug sensitivity across diverse cancers, reinforcing its potential as a biomarker for precision oncology." (PMID 40565566, 2025). "As the first study to elucidate the extensive relationship between TIGD1 and pan-cancer, these findings suggest that TIGD1 may function as an oncogene and serve as a valuable biomarker in cancer diagnostics, therapeutics, and immunotherapy strategies." (PMID 40565566, 2025). "Overall, TIGD1 may play a multifaceted role in promoting carcinogenesis, affecting crucial cellular processes related to gene expression, cellular communication, and homeostasis, with potential interactions between TIGD1, cancer, and the immune response." (PMID 40565566, 2025). "Moreover, TIGD1 exhibits heightened expression across several cancer types, such as colorectal, lung, and pancreatic cancers." (PMID 38651061, 2024). "TIGD1, upregulated in various cancers, including LUSC, lacks a defined function." (PMID 39734333, 2024). "Additionally, integrating multi-omics approaches, including proteomics and metabolomics, may provide deeper insights into the role of TIGD1 in cancer biology." (PMID 40565566, 2025). "qRT-PCR analysis showed that the mRNA expression levels of TIMP1, CDC25C, ATP2A1, and TIGD1 were upregulated in cancer cell lines compared to normal cell lines, whereas NRG1 and DMPK exhibited reduced expression in cancer cell lines." (PMID 41190067, 2025). "TIGD1, a member of the TIGD family of proteins, demonstrates upregulation in eight distinct human cancers, including LUSC." (PMID 39734333, 2024). "Then, a CDM signature with five cancer-dependent genes (MMS19, NOP14, POLRMT, SNAPC5 and TIGD1) and a prognostic nomogram were constructed, and they demonstrated robust predictive performance and a close relationship with clinical characteristics in different CC datasets." (PMID 37441804, 2023).
TIGD1 also shares sentences with these, for which no sentence is quoted: adrenocortical carcinoma (1 paper); astrocytoma (1); bladder urothelial carcinoma (1); cervical squamous cell carcinoma (1); colon adenocarcinoma (1); digestive system carcinoma (1); endocervical adenocarcinoma (1); esophageal carcinoma (1); glioblastoma (1); glioma (1); head and neck squamous cell carcinoma (1); high-grade glioma (1); lymph node metastasis (1); melanoma (1); non-small cell lung carcinoma (1); oligodendroglioma (1); oral cancer (1); pancreatic cancers (1); sarcoma (1); stomach adenocarcinoma (1); testicular germ cell tumor (1); thymoma (1); thyroid carcinoma (1).